CD70 (CD70 molecule)
Diseases named in the same sentence as CD70 in open-access papers (continued):
Sharing a sentence is not in itself a finding about the gene and the disease.
cancer (continued). "Given the encouraging results in other cancer types, CD70-targeted CAR-T therapy holds potential for offering durable and effective treatment options for patients with HNSCC, particularly those with tumors that express high levels of CD70." (PMID 40312353, 2025). "Notably, cancer cells in KIRC exhibited the lowest PIMS and had greater interactions with immune and stromal cells, particularly through CD70 and EDN pathway networks." (PMID 40221501, 2025). "Correlation analysis between RFC4 and checkpoint gene expression in different types of cancers showed a high correlation with immune genes including CCL4, CCL16, HLA family genes, TNFRSF8, TNFRSF14, TNFRSF18, CD70, CD44 (p < 0.05), CD276, CX3CL1 and VGEGFA (p < 0.05)." (PMID 39031628, 2024). "Currently, several ADC targets exist (TROP2, mesotheline, CEACAM5, DLL3, folate receptor alpha, guanylatcyclase, glycoprotein NMB, CD56, CD70 and CD138) with ADC compounds being tested in other cancer entities whose expression level in cervical cancer is of clinical interest." (PMID 38730739, 2024). "This study suggests that CD70, OX40L and 4-1BBL on antigen-presenting B cells promote the differentiation and expansion of antigen-specific cytotoxic T cells that eradicate EBV-related cancers." (PMID 37371066, 2023). "CD70 is a promising pan-cancer antigen that is generally absent in non-lymphoid normal tissue and constitutively expressed on many hematological malignancies and a considerable number of solid carcinomas." (PMID 37475035, 2023). "In diverse cancer types, correlation analysis between CDCA4 and checkpoint gene expression indicated a high connection (P<0.05) with TNF-related immune genes including TNFRSF8, TNFRSF14, TNFRSF18, CD70, CD44, and CD276 (B7-H3)." (PMID 35251007, 2022). "CD70-specific CAR T cells were generated and further shown to be effective in recognizing and killing CD70-positive HNSCC cells but not CD70-negative cancer cells." (PMID 36016159, 2022). "Of these, the average expression of the two genes, including CD70 and PDCD1, and the 12 isoforms derived from the seven genes, including CD40, CD70, IL6, IL10, STAT1, STAT6, and TNFRSF14, were cancer immunotherapy-related genes (false discovery rate (FDR) < 0.01)." (PMID 31292525, 2019). "The purpose of the present study was to assess the effectiveness of genetically modified B-cells co-expressing CD40L in combination with CD70, OX40L, and 4-1BBL to provide costimulatory signals to CD8 T-cells, as an alternative source of autologous APCs for cancer immunotherapy." (PMID 27323820, 2016). "The expression profiling of CD70 in carcinomas has been limited because of the lack of a CD70-specific reagent that works in formalin-fixed paraffin-embedded (FFPE) tissues." (PMID 20664585, 2010). "We also demonstrated that CD70 on RCC cell lines internalises rapidly on specific antibody binding, and that this internalisation can be utilised to transport active cytotoxic molecules into cancer cells." (PMID 16892042, 2006). "Similarly, sCD27, which is strongly expressed in cancers, might interact with these CD27+CD70+ expressing MPs, thereby canceling out the benefits of transfusion." (PMID 36969173, 2023). "It is of great interest to determine whether decreased CD70 expression is a common sign for reduced memory CD8+ T cell function in other chronic viral infections and whether modulating CD70 expression offers a potential means to enhance CD8+ T cell proliferation against infections and cancers." (PMID 36368988, 2022). "Since CD70 expression is absent during homeostasis, as opposed to CD27, it has great potential to exploit as a cancer-specific target." (PMID 34991665, 2022).
hematological malignancies (29 papers, 2015 to 2025). "Overexpression of CD70 has been associated with a variety of hematologic malignancies and solid tumors." (PMID 38730739, 2024). "We aim to advance ADP-520 to clinical study with an eye towards developing a first-in-class autologous and armored CD70-targeted cell immunotherapy for addressing the unmet needs of both hematologic malignancies and solid tumors, such as RCC." (PMID 40519930, 2025). "CD70 is transiently expressed in antigen-activated B-cells, T-cells, NK cells, and mature dendritic cells, but also in hematological malignancies." (PMID 39518937, 2024). "IMM40H exhibited stronger ADCC activity against cells associated with hematological malignancies (Raji, U266B1, Daudi, and Jeko-1 cell lines) compared to competing CD70 mAbs, while also exhibiting potent killing effects against solid tumor cells (A498)." (PMID 37849799, 2023). "CD70, a member of the tumor necrosis factor receptor ligand family, is highly expressed in various solid tumors and hematologic malignancies but has limited expression in normal tissue." (PMID 33121189, 2020). "Anti-CD70 therapies under investigation in hematologic malignancies and solid tumors." (PMID 41510255, 2025). "Worthy of note is the fact that CD70 is also aberrantly expressed on a number of hematological malignancies, leading to the design of CD70-targeting CAR-T cells with a full-length endogenous protein ligand CD27 as the antigen-recognition domain combined with a CD3-ζ chain." (PMID 35053463, 2022). "In addition, mAbs against either CD70 or CD27 have been evaluated in hematological malignancies." (PMID 31186046, 2019). "In hematological malignancies, signaling through the CD27/CD70 axis stimulates cell survival, proliferation, and the acquisition of stemness properties in malignant cells, thereby contributing to disease progression." (PMID 40232798, 2025). "Hematologic malignancies show activated Wnt, JAK/STAT, Hedgehog, and TGF-β pathways that maintain stemness, with CD27 crosslinking and CD70 reverse signaling further driving proliferation." (PMID 40896423, 2025). "CD27 is activated through interaction with CD70 (TNFSF7, also known as CD27L), which is expressed on mature DCs, activated B and T lymphocytes, and certain hematologic malignancies." (PMID 39684559, 2024). "CD27 is stimulated by interaction with CD70 (TNFSF7, CD27L) on mature DCs, activated B and T lymphocytes, and certain hematologic malignancies, and reduces FAS-L-mediated T-cell apoptosis by inducing BCL-XL and PIM-1, thus limiting mitochondrial dysfunction." (PMID 38891056, 2024). "Recently, ADCs, including anti-CD70 mAb or anti-CD27 mAb with azacitidine, have been investigated for treating hematologic malignancies." (PMID 33121189, 2020). "CD70 (CD27L) is a member of the tumor necrosis factor family and is aberrantly expressed on some solid as well as hematological malignancies, including MM." (PMID 31752943, 2019). "We also discuss the basic research and ongoing clinical trials on emerging immune checkpoints (Galectin-9/Tim-3, CD70/CD27, LAG-3, and LILRBs) and on new targets for CAR-T cell therapy (CD22, CD33, CD123, BCMA, CD38, and CD138) for the treatment of hematologic malignancies." (PMID 31186046, 2019). "In a healthy physiological setting, tightly controlled expression of both CD70 and CD27 plays a role in the co-stimulation of the immune response, but malignant cells co-expressing CD70 and CD27 promote stemness, proliferation, and survival of hematological malignancy." (PMID 39518937, 2024). "To determine whether IL-21 also sensitizes LPSCs to cell-based therapies currently used in hematological malignancies, we treated LPSCs from two newly diagnosed patients with AML with CAR T cells targeting the AML surface antigen CD70 in the presence and absence of rh-IL-21." (PMID 39536753, 2024).
infection (16 papers, 2013 to 2025). The state of being infected such as from the introduction of a foreign agent such as serum, vaccine, antigenic substance or organism. "The co-stimulatory molecule CD70 was slightly upregulated upon LOAd infection in all cells, and this was most prominent with transgene-encoding LOAd703." (PMID 33666760, 2021). "CD27 is a TNF receptor that stimulates B cells and promotes their differentiation after being activated by the TNF ligand CD70, thereby promoting anti-infection immunity." (PMID 34646272, 2021). "Receptors and ligands of the TNF superfamily are also expressed transcriptionally following infection in BMDMs including CD70, CD40, OX40L and 41BBL, of which surface expression of OX40L appears most sensitive to induction by T. gondii infection." (PMID 32853276, 2020). "Similar control of IL-2 production from CD4 and CD8 T cells by CD70-dependent signals has been found in other infection models." (PMID 31412088, 2019). "Groups of primed mice were treated with CD70 blocking antibody or an isotype control only during heterosubtypic A/PR8 infection." (PMID 31412088, 2019). "On the invert, infection of LB1319-MEL cells with RhoA-encoding adenoviruses induced RhoA overexpression and increased levels of membrane-associated CD70." (PMID 26828592, 2016). "However, adding CD70 CAR-TOAd−GFP cells to CD70- HA did not cause infection of U251 cells in the bottom compartment." (PMID 40474210, 2025). "To better understand how TS-2021 infection enhances the antitumor efficacy of CAR-T cells, we conducted RNA sequencing on CD70 CAR-T, CD70 CAR-TOAd−GFP, and CD70 CAR-TTS−2021 cells." (PMID 40474210, 2025). "Increased mean fluorescence intensity (MFI) of CD86, MHC-II and CD70 was observed upon overnight incubation of infected DCs with TVH and depending on TCID50 used for infection." (PMID 36997583, 2023). "We asked about the age-dependent expression of the costimulatory molecules CD86, CD80 and CD70 on the surface of CD103+ and CD11b+ DCs in the MLN at three days post-infection with RSV as an indication of their capacity to effectively induce adaptive responses." (PMID 24550729, 2014). "The proliferation and viability of CD70 CAR-T cells infected with OAd-GFP (CAR-TOAd−GFP) did not decrease significantly at six days post-infection." (PMID 40474210, 2025). "CD70 CAR-T cells infected with TS-2021 (using the same transfection method as OAd-GFP) showed higher proliferative capacity and viability within six days post-infection." (PMID 40474210, 2025). "In addition, CD70-expressing immune cells regulate HSPC function and differentiation during infection via CD27 signaling." (PMID 33594067, 2021). "In fact, MHC molecules as well as CD70 and ICAM-1 were rather downregulated upon LOAd infection in general, indicating that transcription levels may in some way be decreased due to the viral replication process." (PMID 32355275, 2020). "Another possibility is that under low dose infection CD70 and OX40L are induced but expression is not high enough or sustained long enough for them to impact on CD8 T cells." (PMID 24205056, 2013). "In contrast, U266-84 cells did not express CD86 and displayed the greatest reductions in CD70 and ICAM-1 upon LOAd infection." (PMID 32355275, 2020).
hematologic cancers (7 papers, 2021 to 2025). "However, solid and hematological cancers express CD70 constitutively, and this expression is associated with a poor prognosis." (PMID 37849799, 2023). "A therapeutic anti-CD70 antibody may have broader applications since aberrant CD70 expression is associated with a poor prognosis in solid and hematologic cancers." (PMID 37849799, 2023). "Despite holding great potential to treat both solid and hematological cancers, CD70 targeting therapies have shown two important limitations: not all patients respond and the occurrence of dose-limiting toxicity." (PMID 37093350, 2023). "Existing companion diagnostics to select patients eligible for anti-CD70 therapy include ex vivo assessment of CD70 expression in solid and hematological tumors by immunohistochemistry and flow cytometry, respectively." (PMID 37093350, 2023). "FACS analysis was used to determine whether IMM40H bound to CD70 on various solid and hematologic tumor cells." (PMID 37849799, 2023). "CD70 is an appealing immunotherapeutic target due to its low expression in non-neoplastic cells, including a limited subset of normal lymphocytes and dendritic cells, and high expression in many hematologic cancers and some solid tumors." (PMID 35565190, 2022). "CD70 is expressed in hematologic cancers as well as in solid tumors." (PMID 36239354, 2022).
hematologic neoplasms (3 papers, 2023 to 2025). "CD70 demonstrates pathognomonic overexpression across diverse solid and hematologic neoplasms, inducing co-stimulation and promoting the differentiation of cytotoxic T lymphocyte cells." (PMID 40715072, 2025). "A phase I study of anti-CD70 CAR-T cells for CD70 positive hematologic neoplasms, including AML, is currently recruiting (NCT04662294)." (PMID 38927401, 2024). "Monoclonal antibodies, antibody-drug conjugates (ADCs), and CAR-T-based treatments have shown that CD70 is the optimal target due to its very limited expression pattern in certain blood cancers and solid tumors." (PMID 37849799, 2023).
CD70 also shares sentences with these, for which no sentence is quoted: multiple myeloma (6 papers); alopecia areata (3); Burkitt lymphoma (3); hepatocellular carcinoma (3); inflammatory bowel disease (3); Behçet's syndrome (2); chronic myeloid leukaemia (2); diffuse malignant mesothelioma (2); influenza (2); lupus erythematosus (2); malignant glioma (2); meningioma (2); myeloid leukaemia (2); neuroblastoma (2); pharyngeal cancers (2); rhabdomyosarcoma (2); systemic sclerosis (2); Thymic Squamous Cell Carcinoma (2); acute lymphoblastic leukemia (1); adenocarcinoma (1); adenoid cystic carcinoma (1); allergic contact dermatitis (1); allergic disease (1); anaplastic astrocytoma (1); anaplastic large cell lymphoma (1); autosomal dominant anhidrotic ectodermal dysplasia (1); Bare Lymphocyte Syndrome (1); Central Nervous System Diffuse Large B-Cell Lymphoma (1); central nervous system infection (1); Chronic Heart Failure (1).
A further 46 diseases each share a sentence with CD70 in 1 paper.